STC2 (stanniocalcin 2)
Diseases named in the same sentence as STC2 in open-access papers (continued):
Sharing a sentence is not in itself a finding about the gene and the disease.
tumor (continued). "In addition, the expression of STC2 in tumor tissues positively correlated with circulating STC2 mRNA levels in LSCC patients." (PMID 24743310, 2014). "Therefore, we can conclude that STC2 mRNA expression is a more promising and reliable blood marker for predicting biological tumor aggressiveness in patients with LSCC." (PMID 24743310, 2014). "Whether STC2 overexpression contributes to tumor progression and distant metastasis remains unknown." (PMID 24606961, 2014). "STC1 and STC2 are involved in tumor progression and metastasis." (PMID 24743310, 2014). "However, the precise role of STC2 in tumor progression and metastasis remains to be investigated by further studies including loss-of-function analysis." (PMID 24606961, 2014). "STC1 and STC2 were expressed predominantly in the cytoplasm or on the membranes of tumor cells." (PMID 24743310, 2014). "As one of the most upregulated genes in response to glutamine or glucose deprivation, STC2 may participate in triggering adaptive tumor metabolism, hence contributing to tumor progression and distant metastasis." (PMID 24606961, 2014). "This might partly explain why STC2 mRNA expression correlates more closely with biological tumor aggressiveness in LSCC." (PMID 24743310, 2014). "STC1 and STC2 are involved in various biological mechanisms of tumor progression." (PMID 24743310, 2014). "Preoperative KAP1, TIMP1 and STC2 expression levels in peripheral blood were related to cancer stage and may be markers of tumor invasion, lymph node metastasis and TNM stage." (PMID 23548070, 2013). "Nonetheless, we observed strong correlations between ER and many genes that have previously been shown to be strongly associated with ER positivity, including GATA3, FOXA1, AGR2, AR, and STC2, in microarray profiling studies of mixed ER-positive and ER-negative tumours." (PMID 17555561, 2007). "In addition, through TCGA, GSE100243, GSE74602, GSE143939, GSE89393, GSE144259 and GSE166427, it is found that STC2 is significantly expressed by tumor samples and the relative mRNA level of STC2 is significantly higher in stage IV, lymph node metastasis and organ metastasis samples." (PMID 40535801, 2025). "Therefore, we believe that malignant cells expressing STC2+ may activate this pathway to create an environment favorable to tumor growth and increase liver metastases in CRC." (PMID 41502509, 2025). "In the TCGA-LIHC cohort, the expression levels and risk scores of STC2 and BIRC5 were positively correlated with the expression level of PDL1, indicated that both STC2 and BIRC5 can promote the expression of PDL1 on cancer cells, thereby promoting tumor immune escape." (PMID 40458412, 2025). "STC2 is substantially stimulated under stress conditions such as ER stress, hypoxia, and nutrient deprivation; the overexpression of STC2 is positively correlated with tumor growth, invasion, metastasis, and poor patient prognosis, highlighting its potential as a biomarker." (PMID 37957902, 2024). "STC2, a member of the glycoprotein hormone-secreting family, promotes the differentiation and mineralization of osteoblasts; inhibits apoptosis; promotes resistance to oxidative damage; promotes the proliferation, survival, and migration of tumour cells; and thus promotes tumour progression." (PMID 35610231, 2022). "Finally, tumour growth was assessed to determine the effects of HOTAIR/miR‐206/STC2 axis in vivo." (PMID 31297902, 2019). "Many studies have shown that STC2 plays an important role in the regulation of colorectal cancer, nasopharyngeal cancer, ovarian cancer, and other solid tumors, such as accelerating the invasion and metastasis of tumor cells, inhibiting cell apoptosis, and so on." (PMID 30962272, 2019). "Similarly, our study confirmed that the STC2 protein was localized in the cytoplasm of tumor cells." (PMID 30962272, 2019). "STC1 or STC2 status may play important roles in tumor biology." (PMID 24743310, 2014).
tumor (continued). "In addition to hypoxia, radiation represents another stress and source of oxidative stress to tumor cells, which may lead to the upregulation of STC2 following IMRT." (PMID 24606961, 2014). "PERK inhibition reduces tumor growth and immunosuppression, while one of it downstream targets, STC2 (stanniocalcin 2), is upregulated in OS tissues and correlates with poorer survival outcomes." (PMID 41228282, 2025). "Conversely, in ER-negative tumors, high STC2 expression may activate alternative stress-response pathways, such as those related to hypoxia, nutrient deprivation, or endoplasmic reticulum stress, which could contribute to a more aggressive tumor phenotype and poorer prognosis." (PMID 40006048, 2025). "RNA was extracted from tumor tissue, and the expression of DEIRGs including GREM2, CTSS, TINAGL1, ACKR1, HLA-DRB1, and STC2 was verified using real-time quantitative reverse transcription PCR (RT-qPCR)." (PMID 39735532, 2024). "We found that genes with a hazard ratio >1 (STC2 and TNFRSF11B) were expressed at higher levels in tumor tissues compared to normal tissues, with a significant and meaningful increase." (PMID 39119088, 2024). "Compared with normal tissues, only SLURP1 was downregulated in tumor tissues, while the expression levels of DKK1, GAST, IGHM, IL12RB2, STC2, and TNFRSF4 were upregulated in tumor tissues." (PMID 39282247, 2023). "Our analysis demonstrated that MYLK2, FAM83D, STC2, CCDC112, EPHX4 and MMP1 were differentially expressed between tumor and normal tissues, with higher expression in tumor tissues than in normal tissues (p < 0.0001)." (PMID 37309005, 2023). "Studies showed that STC2 transcript was upregulated in HCC tissues, and higher serum STC2 level was correlated with larger tumor size and shorter OS and DFS of HCC patients." (PMID 35924040, 2022). "Immunohistochemical (IHC) staining demonstrated that STC2 is mainly expressed in distal tubuli and glomeruli in normal kidney tissues with both cytoplasmic and membranous signals detected in RCC tumours." (PMID 35501821, 2022). "ARID3B, CXCR1, GATS, Itga6, Shh, SLC27A5, STC2, and VEGF play an important role in cell proliferation and tumor progression or metastasis." (PMID 35875133, 2022). "IGF1 was also expressed in the CAFs while IGFR1 was predominantly expressed in the tumor cells: STC1, STC2 and IGFBP4 were expressed in both tumor cells and CAFs." (PMID 35205651, 2022). "The expression of STC2, ESM1, INHBA, CXCL1 and TDGF1 was significantly increased in tumor tissues than in normal tissues, whereas GLP2R expression was higher in normal tissues than in tumor tissues." (PMID 32788867, 2020). "In previous studies, high expression of STC2 protein was reported in HCC, and some of them are suggested to be located in the cytoplasm of tumor cells." (PMID 30962272, 2019). "At the molecular level, it has been shown that STC2 can modulate multiple signaling pathways, such as PI3K/AKT, ERK1/2, in tumor cells and osteoblast." (PMID 30038584, 2018). "In summary, the results presented herein demonstrate that STC2 promotes HNSCC cell proliferation, tumor growth, and metastasis through the PI3K/AKT/Snail pathway." (PMID 27863406, 2017). "High STC2 expression was positively correlated with high-grade tumorigenesis stage for CRC, including tumor size, lymph node metastasis and TNM stage (P < 0.05)." (PMID 27662663, 2016). "STC2 overexpression promoted CRC cell growth and cell migration in vitro, and STC2 enhanced tumor growth in a mouse CRC-xenograft model." (PMID 27662663, 2016). "Relative expression levels of the eight genes of interest (AZGP1, BIRC5, DHCR7, IL6ST, MGP, RBBP8, STC2, and UBE2C) were compared between paired whole tissue sections and tumor-enriched specimens." (PMID 25218890, 2014). "Stanniocalcin 2 (STC2) is overexpressed in several types of human cancers, and its overexpression positively correlates to tumor progression and poor prognosis." (PMID 24606961, 2014).
tumor (continued). "There were significant correlations between KAP1, TIMP1 and STC2 levels, and TNM tumor stages and distant metastases." (PMID 23548070, 2013). "Under endoplasmic reticulum stress, hypoxia, or nutrient deprivation, STC2 is upregulated and activates key survival regulators such as activating transcription factor 4 (ATF4) and HIF-1, thereby inhibiting apoptosis and enhancing tumor cell adaptation." (PMID 41596432, 2026). "Subsequently, using a large number of clinical samples, we conducted IHC staining and found that STC2 expression in tumor tissues was significantly higher than in adjacent non-cancerous tissues." (PMID 39119088, 2024). "Furthermore, DepMap analyses suggested a reverse correlation between STC2 and MAOB expression in a series of human tumour cells." (PMID 38464261, 2024). "To address whether the observation in cell culture is relevant to tumour progression in vivo, we first performed IHC staining and confirmed the elevated expression of MAOB in STC2 knockdown xenografts." (PMID 38464261, 2024). "The results showed that correlation between STC2 and ICP genes varied across tumor types." (PMID 35937984, 2022). "In this study, we identified STC2 as a key gene regulated by PM2.5 based on transcriptome analysis, whose expression correlated to prognosis, immune microenvironment, tumor heterogeneity and stemness, immune checkpoint genes, epigenetic modifications in multiple cancer types." (PMID 36685853, 2022). "Although STC1 has been reported to regulate multiple processes during tumour development and progression, the different expression pattern of STC1 and STC2 indicates they may have different roles under physiological or pathological conditions." (PMID 35501821, 2022). "There is no comprehensive review on the role of STC2 to clarify its functions and potential in various tumor context." (PMID 34612765, 2021). "OLR1, STC2, and DKK1 correlate with tumor evolution and immunosuppressive effects." (PMID 34993138, 2021). "Among these genes, six (HOXA6, STC2, HSD17B8, TFAP2A, CYP1B1, and HOXC8) were reported to be osteogenesis-/chondrogenesis-related genes, and five (ADRA1A, TSPYL5, TES, TNFRSF10D, and MBP) were reported to be tumor-suppressor genes." (PMID 31889115, 2019). "Therefore, we used immunostaining to detect the expression levels of STC2, pAKT, Snail, vimentin, and E-cadherin in a tissue microarray containing tumor samples from 298 HNSCC patients, as well as tissue from 98 non-tumor controls." (PMID 27863406, 2017). "The secreted level of STC2 in CRC patient's plasma can really reflect cancer progression status including lymph node metastasis, tumor TNM stages and overall survival, which was completely consistent with correlations of tissue STC2 expression and clinical significance." (PMID 27662663, 2016). "In this study, we found that STC2 (+) NPC resulted in a higher rate of residual tumors than STC2 (−) group at the completion of initial IMRT, suggesting STC2 overexpression may contribute to tumor cell resistance to radiation therapy." (PMID 24606961, 2014). "Therefore, we investigated whether there were correlations between STC2 expression levels and TMB, MSI, tumor purity and ploidy." (PMID 36685853, 2022). "The STC2 immunohistochemical expression in cases of CRC may be strongly related to some clinicopathological para-meters including histological tumor grade, tumor depth of invasion, lymph node metastasis, tumor Dukes’ stage, the presence of lymphovascular invasion, and perineural invasion." (PMID 35096084, 2022). "Besides, a previous study indicated that STC2 activates ERK/MEK and PI3K/AKT signaling pathways to promote colorectal tumorigenesis and epithelial-mesenchymal transition progression, and the high expression of STC2 in serum and tumor tissues is related to the low survival rate." (PMID 34124251, 2021). "Other bioinformatic analyses also revealed a negative correlation between STC2 and MAOB expression in human tumours." (PMID 38464261, 2024).
tumor (continued). "The levels of glycometabolism-related hub genes (G6PD, CENPA, STC2, and PFKFB4) in tumor samples were higher than those in normal samples (p < 0.001)." (PMID 35938165, 2022). "Moreover, a negative correlation between STC2 and MAOB levels is also identified in human tumour samples." (PMID 38464261, 2024).
cancer (100 papers, 2011 to 2026). A tumor composed of atypical neoplastic, often pleomorphic cells that invade other tissues. "Another metastasis-associated protein is Stanniocalcin 2 (STC2), a glycosylated secretory protein that is detectable in serum and considered a potential biomarker for cancer prognosis." (PMID 41596432, 2026). "Recent studies have highlighted the prognostic value of STC2, associating its overexpression with poor survival outcomes in several cancer types." (PMID 40535801, 2025). "The potential role of PAPP-A2 and STC2 for health and disease, e.g. regarding the risk of cancer and metabolic diseases in adults warrants further investigation." (PMID 38245583, 2024). "By analyzing cancer databases, we examined the variation statistics of STC2 in multiple cancer types, the gene expression of STC2 in relation to TNM Stage, and its association with primary, metastatic, and recurrent cases." (PMID 39119088, 2024). "Spearman correlation analysis was then conducted to explore the associations between STC2 expression and immune checkpoint genes, including both inhibitory and stimulatory factors in pan-cancer analysis." (PMID 38229155, 2024). "Cox regression results suggested that STC2 expression was positively or negatively associated with prognosis in different cancers." (PMID 36685853, 2022). "Meanwhile, we also found that the expression levels of PD-1, PD-L1 and CTLA4 were positively associated with STC2 expression in most cancer types." (PMID 36685853, 2022). "STC2 codes for a glycoprotein associated with human cancer, which can enhance the aggressiveness of cancer." (PMID 35102149, 2022). "An important finding was that STC2 expression was significantly associated with TMB in 15 cancers and MSI in five cancers." (PMID 35937984, 2022). "The GSEA enrichment analysis revealed that STC2 was the focus of many signaling pathways associated with cancer." (PMID 35937984, 2022). "Third, although pan-cancer analysis results support that STC2 expression was associated with immunomodulatory mechanisms and immune cell infiltration, the underlying mechanism remains to be further investigated." (PMID 35937984, 2022). "STC2-enhanced cancer metastasis was associated with an increase in vimentin and decrease in E-cadherin mediated by Snail." (PMID 34612765, 2021). "Current evidence supports the notion that STC2 expression is associated with suppression of apoptosis, and cancer development, and dormancy with later relapse." (PMID 24743310, 2014). "It has been reported that STC2 overexpression is associated with poor prognosis or cancer recurrence in most of the cancers studied." (PMID 24606961, 2014). "The association of STC2 with poor prognosis and aggressive cancer features suggests that STC2 inhibitors could potentially improve patient outcomes." (PMID 40535801, 2025). "STC2 has been implicated in cancer formation in a number of recent studies." (PMID 38460960, 2024). "Accumulating evidence suggests that STC2 is implicated in cancer mechanisms." (PMID 35937984, 2022). "STC2 is involved in calcium and phosphate homeostasis and implicated in the progression of cancer." (PMID 33741523, 2021). "Aberrant expression of stanniocalcin 2 (STC2) is implicated in cancer development." (PMID 32258098, 2019). "Since STC2 is aberrantly hypersecreted in many human cancers and associated with poor prognosis, we hypothesize that STC2 might be a novel anorexic factor in patients with advanced cancers." (PMID 29207625, 2017). "Furthermore, we discovered that STC2 was associated with multiple cancers and pathways in cancer." (PMID 36685853, 2022). "To further analyze the role of STC2 in cancer immune processes, we further performed a comprehensive analysis between STC2 expression and immune status." (PMID 40535801, 2025). "Future research should focus on elucidating the precise mechanisms by which STC2 contributes to cancer progression and exploring its utility in clinical applications." (PMID 40535801, 2025).